CDAN1 (codanin 1)
Description:
May act as a negative regulator of ASF1 in chromatin assembly.
Synonyms: CDA-I; CDAI; CDA1; CDAN1A; DLT; PRO1295
Tractability: Antibody: its Gene Ontology location is reachable by antibodies, with high confidence; UniProt predicts a signal peptide or a membrane-spanning region. PROTAC: ubiquitination databases record sites on it; its protein half-life has been measured.
Gene: Protein-coding gene on chromosome 15 (42,723,544 to 42,737,156, reverse strand). Ensembl gene ENSG00000140326.
Subcellular location: Cytoplasm; Nucleus; Membrane
Subcellular location (Human Protein Atlas): Cytosol; Plasma membrane
Gene Ontology:
Molecular function: protein binding
Biological process: chromatin organization; import into nucleus; intracellular protein localization
Cellular component: cytoplasm; cytosol; endomembrane system; nucleus; plasma membrane; membrane
Genetic constraint (gnomAD): Loss-of-function variants: 105 observed, 135.93 expected, observed/expected ratio (o/e) 0.77, 90% interval 0.66 to 0.91. The synonymous counts are far from expectation, so gnomAD's model fits this gene poorly and the ratio says little. Missense variants: 1,665 observed, 1,542.3 expected, observed/expected ratio (o/e) 1.08, 90% interval 1.04 to 1.12. Synonymous variants: 776 observed, 639.94 expected, observed/expected ratio (o/e) 1.21, 90% interval 1.14 to 1.29.
Gene-disease validity (ClinGen):
ClinGen rates the evidence that CDAN1 causes each of these diseases.
anemia, congenital dyserythropoietic, type 1a (autosomal recessive): Definitive.
Homologues: Orthologues: chimpanzee CDAN1 (99% identical), macaque CDAN1 (98% identical), pig CDAN1 (90% identical), rabbit CDAN1 (90% identical), dog CDAN1 (89% identical), mouse Cdan1 (89% identical), rat Cdan1 (87% identical), guinea pig CDAN1 (80% identical).
Diseases named in the same sentence as CDAN1 in open-access papers:
CDAN1 is named in the same sentence as 15 diseases in open-access papers, as found by Europe PMC text mining. Sharing a sentence is not in itself a finding about the gene and the disease. The quoted sentences say what the papers report.
congenital dyserythropoietic anemia type 1 (7 papers, 2020 to 2026). Congenital dyserythropoietic anemiatype I (CDA I) is a hematologic disorder of erythropoiesis characterized by moderate to severe macrocytic anemia occasionally associated with limb or nail deformities and scoliosis. "CDAN1 variants are associated with congenital dyserythropoietic anemia type 1 (CDA-1), characterized by macrocytic anemia with low-hepcidin iron overload due to ineffective erythropoiesis." (PMID 41595494, 2026). "Codanin-1 (CDAN1) is an essential and ubiquitous protein named after congenital dyserythropoietic anemia type I, an autosomal recessive disease that manifests from mutations in CDAN1 or CDIN1 (CDAN1 interacting nuclease 1)." (PMID 40091041, 2025). "The vast majority of cases of CDA type I are caused by mutations in the CDAN1 gene." (PMID 32239177, 2020). "Congenital dyserythropoietic anemia type I (CDA-I) is a rare hereditary anemia caused by CDAN1 or C15orf41 mutations, with CDAN1-related cases responding to interferon-alpha (IFN-α) therapy." (PMID 40640473, 2025). "Codanin-1 (CDAN1) is an essential and ubiquitous protein named after congenital dyserythropoietic anemia type I (CDA-I), an autosomal recessive disease that manifests from mutations in the CDAN1 or CDIN1 (CDAN1 interacting nuclease 1) gene." (PMID 39149339, 2024). "Also, what is striking is the low expression of CDAN1, a gene involved in congenital dyserythropoietic anemia type I (CDA-I)." (PMID 39519257, 2024). "In summary, we demonstrated for the first time that Cdan1 is required for primitive erythropoiesis, while providing two experimental models for studying the role of Codanin-1 in erythropoiesis and in the pathogenesis of CDA type I." (PMID 34234691, 2021).
anemia (4 papers, 2019 to 2024). A reduction in the number of red blood cells, the amount of hemoglobin, and/or the volume of packed red blood cells. "Whether the non‐haematological manifestations of CDA‐I reflect severe anaemia in utero or are directly due to the effects of a mutated or reduced amount of Codanin‐1, as has been previously suggested, is difficult to ascertain." (PMID 30836435, 2019). "To assess the effectiveness of AAVS1-iABE8e iPSCs in generating mutations in target genes, we designed gRNAs to introduce four mutations associated with human diseases causing severe anemia: KLF1 Y290H and L300P and CDAN1 T884A and F360L." (PMID 38081875, 2023). "We found that Cdan1 erythroid conditional knockout mice displayed severe aberrations of primitive erythropoiesis, leading to severe anemia and death in E12.5–E13.5." (PMID 34234691, 2021). "Since zebrafish has been used as a model of anemia, we explored the role of CDAN1 in zebrafish embryonic erythropoiesis." (PMID 34234691, 2021). "Thus, the low expression found in the CDAN1 gene could contribute to altered erythroid maturation in patients with other types of congenital anemia due to bone marrow failure." (PMID 39519257, 2024).
bone marrow failure syndrome (1 paper, 2024). "Given the frequency of BM failure within the pedigree, we examined known recurrent mutations of inherited bone marrow failure syndromes, such as mutations in genes encoding ribosomal proteins (RP), ALAS2, GATA1, CDAN1, EPO, EPOR, etc.." (PMID 38971858, 2024).
depressive disorder (1 paper, 2023). A melancholy feeling of sadness and despair. "Gene-trait association was mostly seen with SCZ, additionally, TRANK1, ADD3 and CDAN1 were TWAS positive for BD, OSBPL3 for depressive disorder and CACNA1G for ADHD." (PMID 38104115, 2023).
dyserythropoietic anemia (1 paper, 2021). "Cdan1 functions in chromatin assembly with mutations in the gene linked to congenital dyserythropoietic anemia." (PMID 34794440, 2021).
iron overload (1 paper, 2026). "Although we detected a likely pathogenic CDAN-1 variant in an asymptomatic subject, its potential role in counteracting the TMPRSS6 defect via low-hepcidin induced iron overload is considered rare and unlikely." (PMID 41595494, 2026).
melanoma (1 paper, 2020). A malignant, usually aggressive tumor composed of atypical, neoplastic melanocytes. "Our signature consists of diverse genes comprising protective (ATP1B1, CDAN1, FAU, and TNFSF14)) and risky (GPR87, KIT, SH3GL3, and PVRL1), which could be considered gene-related protective and risk patterns in melanoma." (PMID 32411243, 2020). "In our study, we identified two gene expression patterns and generated an 8-gene-based (GPR87, KIT, SH3GL3, PVRL1, ATP1B1, CDAN1, FAU, and TNFSF14) gene signature that could recognize melanoma patients with a high risk of unfavorable clinical outcomes." (PMID 32411243, 2020). "Finally, eight genes (GPR87, KIT, SH3GL3, PVRL1, ATP1B1, CDAN1, FAU, and TNFSF14) were identified to be closely associated with the OS in melanoma." (PMID 32411243, 2020). "We identified an 8-gene signature (i.e., GPR87, KIT, SH3GL3, PVRL1, ATP1B1, CDAN1, FAU, and TNFSF14) with independent prognostic value on melanoma." (PMID 32411243, 2020). "All eligible gene sets were analyzed, and the 8 genes (GPR87, KIT, SH3GL3, PVRL1, ATP1B1, CDAN1, FAU, and TNFSF14) with the greatest prognostic impact on melanoma." (PMID 32411243, 2020).
osteosarcoma (1 paper, 2019). A usually aggressive malignant bone-forming mesenchymal neoplasm, predominantly affecting adolescents and young adults. "Previous studies on osteosarcoma U-2-OS cells silenced for Codanin-1 showed accelerated DNA replication rate and increased levels of chromatin-bound Asf1, suggesting that Codanin-1 guards a limiting step in chromatin replication." (PMID 31191338, 2019).
pulmonary hypertension (1 paper, 2021). Increased pressure within the pulmonary circulation due to lung or heart disorder. "In CDA type I, predominantly caused by biallelic mutations in the CDAN1 gene (Codanin 1), chronic anemia is accompanied by hepatosplenomegaly, jaundice and secondary complications, including pulmonary hypertension and IO." (PMID 33672223, 2021).
CDAN1 also shares sentences with these, for which no sentence is quoted: bone marrow failure (1 paper); congenital dyserythropoietic anemia (1); Failure to thrive (1); hereditary anemia (1); hydrops (1); macrocytic anemia (1).